FAF1 (Fas associated factor 1)
Diseases named in the same sentence as FAF1 in open-access papers (continued):
Sharing a sentence is not in itself a finding about the gene and the disease.
Parkinson disease (6 papers, 2015 to 2024). A progressive degenerative disorder of the central nervous system characterized by loss of dopamine producing neurons in the substantia nigra and the presence of Lewy bodies in the substantia nigra and locus coeruleus. "Not only Fas-associated factor (FAF)-1 was a member of the Fas death-inducing signaling complex, but it was involved in various biological processes and played an essential role in cancer, asbestos-induced mesotheliomas, and Parkinson's disease." (PMID 30915356, 2019). "In patients with Parkinson’s disease, FAF1 is overexpressed in dopaminergic neurons in the substantia nigra." (PMID 38474516, 2024). "Fas-associated factor 1 (FAF1), a Fas-binding protein, is implicated in neuronal cell death in Parkinson’s disease (PD)." (PMID 32676027, 2020). "FAF1 has also been found to be overexpressed in the frontal cortex of Parkinson’s disease (PD) as well as PD and AD patients." (PMID 28539126, 2017). "The gene is homologous to human FAF1/TNFRSF6 which is associated with diabetes and Parkinson's disease (PD)." (PMID 26178806, 2015). "A small molecule inhibitor for FAF1 is in clinical development for Parkinson’s Disease, however, no FAF1 stabilizer or activator is known to date." (PMID 39334449, 2024).
type 2 diabetes (5 papers, 2015 to 2026). "Strikingly, recent studies found that FAF1 rs17106184 was susceptibility loci associated with type 2 diabetes by genetic association analysis and validation, but the specific mechanism was unclear." (PMID 33510836, 2021). "The risk allele for type 2 diabetes of rs17106184 in FAF1 was nominally associated with an increase in the HOMA-IR value (0.0083 ≤ p < 0.05 adjusted for sex, age and BMI)." (PMID 27115357, 2016). "The type 2 diabetes risk G-allele of FAF1-rs17106184 associated with increased levels of 2-hour serum insulin (n=5,547, β=0.055, p=0.017) in Inter99 and also when combining effects with three additional Danish studies (n=6,260, β=0.062, p=0.0040)." (PMID 25799151, 2015). "Several studies revealed that FAF1 variations were susceptibility loci associated with type 2 diabetes, but whether the expression of FAF1 was associated with the progression of type 2 diabetes was unclear." (PMID 33510836, 2021). "On this basis, it is worth further investigating whether FAF1 participates in the pathogenesis of metabolic disorders and insulin resistance-associated type 2 diabetes." (PMID 33510836, 2021). "We confirmed associations with type 2 diabetes for five of the seven SNPs (TMEM154-rs6813195, FAF1-rs17106184, POU5F1/TCF19-rs3130501, ARL15-rs702634 and ABCB9/MPHOSPH9-rs4275659)." (PMID 25799151, 2015). "A trans-ethnic meta-analysis of type 2 diabetes genome-wide association studies has identified seven novel susceptibility variants in or near TMEM154, SSR1/RREB1, FAF1, POU5F1/TCF19, LPP, ARL15 and ABCB9/MPHOSPH9." (PMID 25799151, 2015). "We examined the association of six SNP loci, rs6813195 near TMEM154, rs9505118 in SSR1, rs17106184 in FAF1, rs3130501 in POU5F1, rs702634 in ARL15, and rs4275659 near MPHOSPH9, identified by transethnic GWAS meta-analysis with susceptibility to type 2 diabetes in a Japanese population." (PMID 27115357, 2016). "We performed a replication study in a Japanese population to evaluate the association between type 2 diabetes and six susceptibility loci (TMEM154, SSR1, FAF1, POU5F1, ARL15, and MPHOSPH9) originally identified by a transethnic meta-analysis of genome-wide association studies (GWAS) in 2014." (PMID 27115357, 2016). "Many additional gene products linked to ER quality control–dependent ubiquitin-proteasomal proteolysis also show genetic evidence of linkage to human type 2 diabetes (such as EDEM3, UFD1, NPL4, BAG1, and FAF1)." (PMID 41252202, 2026).
cervical carcinoma (3 papers, 2012 to 2023). A carcinoma arising from either the exocervical squamous epithelium or the endocervical glandular epithelium. "Furthermore, nearly 30% of uterine cervix carcinomas have a genomic loss at the FAF1 locus." (PMID 37999107, 2023). "In another study miR-24 acted as an oncomiR negatively regulating p16 in cervical carcinoma cells and the pro-apoptotic FAF1 protein in prostate, gastric and HeLa cancer cells." (PMID 23229173, 2013).
mantle cell lymphoma (3 papers, 2016 to 2023). Mantle cell lymphoma is a rare form of malignant non-Hodgkin lymphoma affecting B lymphocytes in the lymph nodes in a region called the ``mantle zone''. "FAF1 deficiency has been linked to uterine cervical carcinoma, mantle cell lymphoma, and malignant mesothelioma." (PMID 37999107, 2023). "Recurrent mono-allelic and homozygous deletion of FAF1 has been discovered in mantle cell lymphoma." (PMID 37999107, 2023). "Fas-associated factor 1 (FAF1), a 74-kDa pro-apoptotic protein also known as Fas antigen, is involved in diverse biological processes, and its loss has been reported in uterine cervical carcinoma, mantle cell lymphoma and malignant mesothelioma." (PMID 28030825, 2017).
non-small cell lung carcinoma (3 papers, 2022 to 2024). A group of at least three distinct histological types of lung cancer, including non-small cell squamous cell carcinoma, adenocarcinoma, and large cell carcinoma. "In contrast, miR-26a-5p was found to serve as an oncogenic miRNA in non-small cell lung cancer by targeting FAF1." (PMID 38446584, 2024). "On the other hand, among the prooncogenes, miR-26a-5p acts as an oncogenic microRNA in non-small-cell lung cancer by targeting FAF1 and might function as a possible therapeutic target." (PMID 36262998, 2022).
Osteochondrosis (3 papers, 2022 to 2025). Abnormal growth ossification centers in children. "FAF1 gene was associated with dysfunctions of bone and joints in pigs and can lead to osteochondrosis." (PMID 38911262, 2024). "FAF1 has been associated with osteochondrosis of the proximal radius and ulna and the distal humerus in pigs." (PMID 36531249, 2022). "Polymorphisms in Fas-associated factor 1 (FAF1) gene which enhances apoptosis, and parathyroid hormone type I receptor (PTH1R) gene which regulates cartilage growth and chondrocytic apoptosis, were associated with osteochondrosis lesions in pigs." (PMID 41465565, 2025).
virus infection (3 papers, 2017 to 2024). "Upon virus infection, IKKε causes FAF1 degradation by direct phosphorylation at serine 556, resulting in its release from MAVS." (PMID 39167082, 2024). "In particular, we identified the physiological role of FAF1 in innate immune responses against viral infection in FAF1+/+ and FAF1gt/gt mice." (PMID 28542569, 2017). "Panel A, FAF1 mRNA expression levels were increased after viral infection, however, this increase varied according to cell type." (PMID 28542569, 2017). "Virus titers and cytokine levels in FAF1 knockdown MEFs and FAF1-reconstituted MEFs were compared after virus infection (panels E-F-G)." (PMID 28542569, 2017). "Taken together, these data suggest that knockdown of FAF1 inhibited the immune responses by reducing IFN secretion in response to viral infection, thereby facilitating virus replication." (PMID 28542569, 2017). "The serum of FAF1gt/gt mice contained more replicating virus and lower levels of IFN-β and IL-6 than that of FAF1+/+ mice, indicating that knockdown of FAF1 suppresses cytokine secretion upon virus infection." (PMID 28542569, 2017). "We also examined the time course binding of NLRX1 and MAVS and compared it with that of NLRX1 and FAF1 after the virus infection." (PMID 28542569, 2017). "Furthermore, virus infection is postulated to prevent aggregation of FAF1, which inhibits FAF1-dependent suppression of MAVS and then activates antiviral immunity." (PMID 37670988, 2023). "More studies are needed to confirm the role of FAF1 cleavage in virus infection." (PMID 37670988, 2023). "However, after virus infection, FAF1 appears to displace MAVS from NLRX1 by competitive binding to NLRX1." (PMID 28542569, 2017). "Additionally, THP-1 cells (a human immune cell line) were transfected with siRNA targeting FAF1, and virus replication and cytokine levels were measured after virus infection (panels D-E-F-G)." (PMID 28542569, 2017). "This supports our time course binding studies, which showed that FAF1 binds to NLRX1 at early time points (2 and/or 4 hpi) after virus infection." (PMID 28542569, 2017). "After virus infection or Poly (I:C) stimulation, FAF1gt/gt mice showed lower levels of cytokine production (IL-6 and IFN-β) than FAF1+/+ mice, which strongly supporting an impaired antiviral immune response, especially with respect to type I IFN signaling." (PMID 28542569, 2017).
fibrosarcoma (2 papers, 2016 to 2023). A malignant mesenchymal fibroblastic neoplasm affecting the soft tissue and bone. "It has been shown that incubation of murine tumor cells (methylcholanthrene-induced fibrosarcoma (Meth A) and CMS-5) with CP agonist reduces the cellular level of the TRPV1 associated protein FAF1." (PMID 27754413, 2016).
glioma (2 papers, 2014 to 2019). A benign or malignant brain and spinal cord tumor that arises from glial cells (astrocytes, oligodendrocytes, ependymal cells). "However, when the induced apoptosis drugs C18H17NO6 and their combination with Scutellarin were administrated, the expression of FAF1 and its function in glioma have been unknown." (PMID 30915356, 2019).
Listeria infection (2 papers, 2019 to 2021). "Here, we show that FAF1 plays a pivotal role in activating NADPH oxidase in macrophages during Listeria monocytogenes infection." (PMID 31412082, 2019).
orofacial cleft (2 papers, 2014 to 2023). A disorder of facial skeleton that is characterized by cleft lip and/or cleft palate that result in feeding, speech and hearing problems caused by failures during development. "The BP at 1p34 mapped within the first intron of FAF1, and investigation of the possible role of this gene in orofacial clefting was the focus of the original report." (PMID 24363063, 2014).
ovarian carcinoma (2 papers, 2016 to 2019). A malignant neoplasm originating from the surface ovarian epithelium. "Expression analyses of Fas-associated factor 1 (FAF1) and heat shock protein 70 (HSP70) revealed lower expression of FAF1 while concurrent increase in HSP70 levels in ovarian cancer compared to their levels in normal ovary." (PMID 31540420, 2019). "While FAF1 expression is low in ovarian cancer, the expression of HSP70 shows a significant increase in ovarian cancer in comparison to that in a normal ovary." (PMID 27754413, 2016). "The opposite correlation between the expression of FAF1 and HSP70 in ovarian cancer highlights the prognostic and therapeutic potential of FAF1 in patients with ovarian cancer." (PMID 27754413, 2016).
prostate carcinoma (2 papers, 2012 to 2022). A carcinoma that arises from epithelial cells of the prostate gland. "MiR-24 has been reported to target the FAF1 gene in the prostate cancer cell line DU-145." (PMID 23304123, 2012).
squamous cell carcinoma (2 papers, 2012 to 2023). A carcinoma arising from squamous epithelial cells. "Diverse FAF1 expression levels within adenocarcinoma and squamous cell carcinoma were presented." (PMID 37999107, 2023). "As a result, in all 1411 cases, high FAF1 expression was significantly associated with poor prognosis (p = 0.0011), a similar result was shown in the adenocarcinoma cohort (n = 672, p = 0.027), but not in the squamous cell carcinoma cohort (n = 527, p = 0.52)." (PMID 37999107, 2023).
breast adenocarcinoma (1 paper, 2024). "SCP2 was also involved in recurrent fusions with ECHDC2 and FAF1 in breast adenocarcinomas." (PMID 39038933, 2024).
Crohn disease (1 paper, 2023). A gastrointestinal disorder characterized by chronic inflammation involving all layers of the intestinal wall, noncaseating granulomas affecting the intestinal wall and regional lymph nodes, and transmural fibrosis. "Furthermore, single-nucleotide polymorphism testing revealed that FAF1 may be linked to a genetic locus implicated in susceptibility to Crohn’s disease, an inflammatory bowel disorder associated with an increased risk of colorectal cancer." (PMID 37999107, 2023).
diabetes (1 paper, 2015). "The impact of the diabetes risk G-allele of FAF1-rs17106184 on increased 2-hour insulin levels is however unexplained." (PMID 25799151, 2015).
familial colorectal cancer (1 paper, 2023). Familial colon cancer is a cluster of colon cancer within a family. "A somatic FAF1 mutation was discovered in a case of recurrent sarcoma, and germline mutations of FAF1 were recently discovered in hereditary colorectal cancer." (PMID 37999107, 2023). "Recently, germline FAF1 mutations have been discovered in familial colorectal cancer (CRC), and these variants encode an unstable form of FAF1 that increases the resistance of CRC cells to apoptosis." (PMID 37999107, 2023).
fibromyalgia (1 paper, 2023). A chronic disorder of unknown etiology characterized by pain, stiffness, and tenderness in the muscles of neck, shoulders, back, hips, arms, and legs. "Several genes/loci have been reported more than once in CWP, fibromyalgia, and MCP, including EXD3, SLC39A8, AMIGO3/GMPPB/RNF123, C6orf106, FAF1, SLC24A3, and LINC01065/LINC00558." (PMID 37144689, 2023).
glaucoma (1 paper, 2018). Increased pressure in the eyeball due to obstruction of the outflow of aqueous humor. "The crucial role of FAF1 in both ischemic and oxidative stress-induced cell death highlights its essential contribution as a robust mediator of glaucoma progression." (PMID 30200976, 2018).
glioblastoma (1 paper, 2014). The most malignant astrocytic tumor (WHO grade IV). "These intragenic deletions included those targeting known tumour suppressors in glioblastoma such as NF1 (17q11.2, n = 2) and RB1 (13q14.2, n = 1), as well as putative novel GBM-associated genes including FAF1 (1p33, n = 2) and MTAP (9p21.3, n = 2)." (PMID 24548782, 2014).
glucose metabolism disorder (1 paper, 2021). "FAF1 mediated hepatic metabolic disorder via interaction with JNK and impairment of the insulin signaling pathway, thereby leading to aggravated glucose metabolism disorder, lipid metabolism disorder, and insulin resistance." (PMID 33510836, 2021).
Headache (1 paper, 2022). Cephalgia, or pain sensed in various parts of the head, not confined to the area of distribution of any nerve. "Of the genes at these loci, six (FAF1, TMX2-CTNND1, AARSD1, PLCD3, ZNF652, and C20orf203; headache-TSH) and six (HMGB1P45, RPL30P1, ZNF462, TMX2-CTNND1, ITPK1, SECISBP2L; headache-fT4) were significant in our gene-based analysis (pFisher’s combined p-value < 2.09 × 10−6)." (PMID 36672757, 2022).
Hyperinsulinemia (1 paper, 2021). An increased concentration of insulin in the blood. "Another unfavorable effect of hyperinsulinemia was identified by a downregulation of FAF1 in the present study, which was found to increase tumorigenesis, as FAF1 plays a role in various biological processes including apoptosis." (PMID 33690729, 2021).
Hypodontia (1 paper, 2023). The absence of five or less teeth from the normal series by a failure to develop. "There was a significant association between the D1S197 (1p33-32.3) markers containing the FAF1 gene among NSCL/P subjects with or without hypodontia compared with the noncleft subjects (p-value = 0.023)." (PMID 38031027, 2023).
influenza (1 paper, 2025). An acute viral infection of the respiratory tract, occurring in isolated cases, in epidemics, or in pandemics; it is caused by serologically different strains of viruses (influenzaviruses) designated A, B, and C, has a 3-day incubation period, and usually lasts for 3 to 10 days. "In addition to the regulation of NLRX1 function by FAF1 during influenza infection, NLRX1 driven antiviral signaling can also be attributed to the attenuation of viral protein translation." (PMID 40356929, 2025).
Insulin resistance (1 paper, 2021). Increased resistance towards insulin, that is, diminished effectiveness of insulin in reducing blood glucose levels. "In conclusion, our study elucidates the biological effects and underlying mechanism of FAF1 in metabolic disorder and insulin resistance." (PMID 33510836, 2021). "Although it is well accepted that FAF1 has a vital role in various biological processes, its underlying mechanism in metabolic disorders and insulin resistance remains unclear." (PMID 33510836, 2021). "These novel findings highlight FAF1 as a key meditator of hepatic metabolic disorder and insulin resistance." (PMID 33510836, 2021). "Our data indicate that FAF1 is a potent regulator in hepatic metabolic disorder and insulin resistance." (PMID 33510836, 2021). "This study aims to elucidate the role and the molecular mechanism of FAF1 in hepatic insulin resistance." (PMID 33510836, 2021). "Considering that FAF1 overexpression impaired glucose and lipid metabolic perturbation, we further explored the effect of FAF1 overexpression on hepatic insulin resistance." (PMID 33510836, 2021). "In short, the expression of hepatic FAF1 protein was increased in the state of insulin resistance, thus suggesting a potential role of FAF1 in hepatic metabolism disorder." (PMID 33510836, 2021). "While it is well accepted that FAF1 has a role in various biological processes, its role in metabolic disorders and insulin resistance is unclear." (PMID 33510836, 2021). "Using a specific JNK inhibitor (SP600125) that could block the kinase activity of JNK, we demonstrated a beneficial effect of JNK inhibition on the insulin signaling pathway and an indispensable role of its activation in FAF1-exacerbated insulin resistance." (PMID 33510836, 2021). "Although the relationship between Fas and insulin resistance has been widely studied, it remains unknown whether FAF1, a Fas-binding protein, may be involved in hepatic metabolic disorders and insulin resistance." (PMID 33510836, 2021). "In the present study, we identified FAF1 as a novel regulator in hepatic insulin resistance." (PMID 33510836, 2021). "It remains unclear, however, whether FAF1 is involved in hepatic metabolic disorder and insulin resistance." (PMID 33510836, 2021). "Our study found that FAF1 overexpression increased ROS production, which might be involved in insulin resistance." (PMID 33510836, 2021). "Mechanistically, FAF1 interacts directly with c-Jun N-terminal kinase (JNK) and activates its phosphorylation, thereby blocking the downstream insulin signaling pathway and leading to insulin resistance." (PMID 33510836, 2021). "However, the correlation of FAF1 with JNK in hepatic insulin resistance has not been investigated." (PMID 33510836, 2021).
ischemic disease (1 paper, 2018). Lack of blood supply to an area of the body, resulting in impairment of tissue oxygenation. "We investigated whether FAF1 is involved in the pathogenesis of ischemic diseases using a retinal ischemia model." (PMID 30200976, 2018). "Collectively, we suggest that developing a FAF1 inhibitor might offer a new opportunity for the treatment of various ischemic diseases." (PMID 30200976, 2018).
leiomyosarcoma (1 paper, 2024). An uncommon, aggressive malignant smooth muscle neoplasm, usually occurring in post-menopausal women. "The loss of FAF1 function may affect the activity of the constitutive Wnt pathway and promote the occurrence of leiomyosarcoma." (PMID 38365777, 2024).
lentivirus infection (1 paper, 2017). Virus diseases caused by the Lentivirus genus. "Lentivirus infection on its own did not affect FAF1 expression levels, since levels were similar between HGC-27/NC and HGC-27 cells (P = 0.58)." (PMID 28030825, 2017).
lipid metabolic disorder (1 paper, 2021). "In the current study, we show that FAF1 overexpression dramatically exacerbates glucose and lipid metabolic disorder, as well as insulin resistance by contributing to JNK activation in hepatocytes." (PMID 33510836, 2021).